SIRT1 (sirtuin 1)
Diseases named in the same sentence as SIRT1 in open-access papers (continued):
Sharing a sentence is not in itself a finding about the gene and the disease.
tumor (continued). "Researchers have explored pathways to activate or inhibit SIRT1, given its critical regulatory impact on tumor promotion and suppression." (PMID 39403142, 2024). "SIRT1 is both a tumor suppressor and a tumor promoter, which depends on cell type and SIRT1 localization." (PMID 38784035, 2024). "Future studies should focus on the interaction between SIRT1 and the Wnt signaling pathway, as well as its role in different tumor microenvironments." (PMID 39845948, 2024). "This cascade amplifies PCa cell invasiveness, mediated by the miR21/TLR8 axis, underscoring SIRT1’s role in immune evasion and tumor aggressiveness." (PMID 39796040, 2024). "Research indicates that SIRT1 influences key processes such as cell proliferation, migration, invasion, and colony formation, thereby mediating tumor development and contributing to drug resistance." (PMID 39598398, 2024). "Concluding its tumor suppressive role in EOC via targeting sirtuin 1 (SIRT1), miR-494 was shown to have a promising role in EOC treatment." (PMID 38690293, 2024). "The role of SIRT1 in aging and tumorigenesis, acting as a tumor suppressor or tumor promoter, seems to be influenced by the intracellular localization and the cell types." (PMID 39056701, 2024). "By enhancing the activity of pro-survival factors and inhibiting apoptotic signals, SIRT1 supports tumor progression." (PMID 39682281, 2024). "SIRT1 is mainly located in the nucleus, but can shuttle to the cytoplasm during neuronal development, differentiation, and in situations where tumor cells are present." (PMID 39683482, 2024). "Intriguingly, serum MEG3 expression level was negatively correlated with tumor stage (r = − 0.224, P = 0.049), while there was a positive correlation between serum SIRT1 levels and the anatomical site (r = 0.28, P = 0.023)." (PMID 38704452, 2024). "Its knockdown enhances apoptosis, while downregulating SIRT1 expression in TRAIL-treated cells, indicating a TRAF2/SIRT1 axis that supports tumor survival and growth." (PMID 39796040, 2024). "In this study, we aimed to investigate the impact of Sirt1 expression on various factors, including age, gender, tumor size, and metastasis." (PMID 38427808, 2024). "Recently, sirtuins (SIRT1–7) have demonstrated a great potential as biomarkers and/or targets for the treatment of BCs and the dual role of SIRT1–7 as tumor promoters or suppressors in BCs have been widely discussed." (PMID 36835056, 2023). "To assess the impact of SIRT1-knockdown on tumor growth and DDP resistance in vivo, we introduced either control or SIRT1-knockdown T24/DDP cells into the axillary region of BALB/c nude mice, thereby establishing a xenograft model." (PMID 38201552, 2023). "SIRT1 can activate various anti-apoptotic pathways, inhibit the cell cycle, and enhance tumor growth." (PMID 37180577, 2023). "A study in a tumor-bearing rat model showed that doxorubicin decreased SIRT1 expression, and melatonin cotreatment attenuated the reduction of SIRT1 expression in this model." (PMID 36986646, 2023). "Previous studies have found that directly or indirectly reducing or increasing the expression of SIRT1 in tumor cells significantly impacted the cells’biological behavior." (PMID 37293593, 2023). "The mechanisms that SIRT1 exhibits in pathologies are complex due to the display of both tumor suppression and tumor-promoting features, as well as an observed dose-dependent effect on different cellular processes." (PMID 37456463, 2023). "The exact nature of the multiple functions of Sirt-1 signaling in carcinogenesis is still a matter of debate, as Sirt-1 can act as both a tumor enhancer and a repressor." (PMID 37575245, 2023). "In sync with previous studies, our findings showed that SIRT1 facilitates the proliferation and migration of tumor cells in ICC." (PMID 36691046, 2023).
tumor (continued). "In an orthotopic rat CCA model, the inhibitor of sirtinol (SIRT1) reduced tumor size and tumorigenic protein expression." (PMID 37510333, 2023). "Recently, SIRT1 has been intensively studied in medical oncology, but the role of SIRT1 is still controversial, as it has been proposed as both an oncogene and a tumor suppressor." (PMID 37627400, 2023). "SIRT1 indicates the frequency of glucolipid transformation and rapid tumor progression and is a promising therapeutic target of CRC." (PMID 37063423, 2023). "Hypoxia induction in a steroidogenic human ovarian granulosa-like tumor cell line (KGN) resulted in the downregulation of SIRT1, PGC-1α, and mtDNA, an effect that was reversed by resveratrol through SIRT1-mediated deacetylation and activation of PGC-1α." (PMID 36237161, 2023). "Significant upregulation of SIRT1 promotes tumor proliferation, migration, and invasion by targeting SREBP1 and lipogenesis in EC." (PMID 38189049, 2023). "In other words, Sirt1 O/E in pneumocytes can affect several tumor suppressor genes or oncogenes, which can indirectly affect Kras tumor development." (PMID 37779142, 2023). "The aim was to validate the importance of the transformation of glucolipid metabolism in tumor development and the therapeutic potential of SIRT1 interference in CRC patients." (PMID 37063423, 2023). "According to reports, the deacetylation of Foxk 2 by SIRT1 reduces tumor chemosensitivity to cisplatin." (PMID 38201552, 2023). "Exosomes containing miR-23a secreted by tumor cells promote tumor microvasculogenesis by acting on SIRT1 in EC." (PMID 37178254, 2023). "Further, it was noted that SIRT1 showed the most pronounced difference and was reported to be close to tumor progression among the candidate genes." (PMID 36691046, 2023). "TNM plot analysis revealed that both VDR and SIRT1 gene expression decreased from normal to tumour colonic tissue in a highly significant fashion (p<0.001)." (PMID 37530744, 2023). "Cell viability was determined by CCK8 assays, from which we observed that downregulation of SIRT1 notably inhibited tumor cell growth in ICC." (PMID 36691046, 2023). "SIRT1 upregulation was significantly associated with several aggressive clinicopathological features of CRC, such as large tumor size and high recurrence and metastasis rates." (PMID 37063423, 2023). "Metabolic reprogramming is a feature of tumor growth, and SIRT1 regulates several genes involved in glucose and lipid metabolism." (PMID 37715252, 2023). "Depending on the organ or even the species, SIRT1 has the ability to function as either a tumor suppressor or a tumor promoter." (PMID 37242510, 2023). "The level of VDR protein was usually lower in tumour samples, while SIRT1 protein expression showed high variability between tumors and high cellular intratumor heterogeneity." (PMID 37530744, 2023). "Research has shown that SIRT1 regulates stress responses indicating that it can also be a tumor suppressor." (PMID 38006398, 2023). "The comparison among vehicle cryopass-laser and melatonin cryopass-laser-treated xenografts showed that SIRT1 immunopositivity is up-regulated in the vehicle-treated tumor cells with a significant difference compared to melatonin-treated tumors." (PMID 37894275, 2023). "Studies have shown that the expression of SIRT2, SIRT3, SIRT6, and SIRT7 is increased in tumor-stage 1-4 subgroups, SIRT1 expression is increased in tumor-stage 1, and the expression of SIRT4 is decreased." (PMID 37096064, 2023).
tumor (continued). "In non-tumor cells, several effects of melatonin are abolished by inhibiting SIRT1 expression, which indicates mediation by SIRT1." (PMID 37507744, 2023). "Sirt1, which is overexpressed in tumor cells, is correlated with the silencing of tumor suppressor genes and with cancer resistance to chemotherapy." (PMID 36768253, 2023). "We discovered downregulation of mito-fusion protein OPA1 (mitochondrial dynamin-like 120-kDa protein) and MFN2 (mitofusin-2) and upregulation of mito-fission protein DRP1 (dynamin-related protein 1) in tumor cells with SIRT1 KO." (PMID 37063423, 2023). "The anti-aging gene Silent information regulation 1 (SIRT1) regulates glycolipid metabolism, inflammatory response, cell death and apoptosis, oxidative stress, and tumor formation." (PMID 38027119, 2023). "In this study, we found that EA improved CRC symptoms, activated SIRT1 and autophagy to inhibit miR-215, leading to the inhibiting of tumor growth in the CRC." (PMID 38006398, 2023). "Here, we investigated the impact of transdermal melatonin on the tumor dimension, microenvironment structure, and SIRT1-modulated pathways." (PMID 37894275, 2023). "The immunohistochemistry analyses confirmed that the expression of VIRMA, SIRT1, and Ki67 was upregulated in the tumor tissues with CCL3 stimulation, and it was also reversed in the tumor tissues with VIRMA down-expression." (PMID 36691046, 2023). "The addition of the SIRT1 inhibitor EX527 into the tumor cell culture system significantly increased the apoptotic ratio." (PMID 37063423, 2023). "It has been shown that metformin-induced pyroptosis is activated through AMPK/silent information regulator 1 (SIRT1) pathway in tumor cells, where increased NFκB p65 stimulates Bax and cytochrome C release." (PMID 36737598, 2023). "We cultured CRC cells in a sugar-free or H2O2-supplemented medium and observed that SIRT1 upregulation stabilized the condition of tumor cells under stress stimulus." (PMID 37063423, 2023). "The upregulation of SIRT1 by SRT1720 (a known SIRT1 activator) attenuates melatonin’s antioxidant and antitumor activity, indicating that its induction of ROS production in tumor cells is activated by SIRT1." (PMID 36768253, 2023). "Together, these data demonstrated that CCL3 promotes the growth of ICC cells by regulating VIRMA/SIRT1 in ICC subcutaneous tumor mice model." (PMID 36691046, 2023). "We then conducted a CCK-8 assay to establish the effects of SIRT1 on tumor cell proliferation under stress conditions." (PMID 37063423, 2023). "The ectopic expression of miR-494 effectively restrains tumor cell proliferation, invasion, and resistance to 5-FU by directly targeting SIRT1 and c-Myc." (PMID 38139352, 2023). "Based on a semi-quantitative assessment of the SIRT1 immunoreactive cells, the SIRT1 protein expression levels correlated inversely with the degree of tumor differentiation." (PMID 37627400, 2023). "In CSCs, NAMPT regulates epithelial-mesenchymal transition (EMT) and tumor dedifferentiation/reprograming via controlling cellular functions that promote proliferation and pathways mediated by SIRT1 and PARP1." (PMID 36819783, 2023). "The overexpression of miR-34a-5p, a tumor-suppressor miRNA, inhibits SIRT1 and upregulates SIRT1 effector-acetylated FOXO1, suppressing angiogenesis by inducing the senescence of endothelial progenitor cells." (PMID 36835100, 2023). "Several studies have reported that c-MYC increased the expression and activity of SIRT1 mediated via transcriptional activation of NAMPT to drive tumor cell proliferation and progression." (PMID 38116009, 2023).
tumor (continued). "SIRT1 was shown to be a potential tumor promoter based on its role in negatively regulating many tumors suppressors." (PMID 36691046, 2023). "This explains its anti-proliferative effect in this study, as SIRT1 can modulate the activity of proteins necessary for oncogenesis and enhance tumor proliferation and progression as well as drug resistance." (PMID 37338718, 2023). "We confirmed the synergistic anticancer effect of EX527 by SIRT1 IHC staining and by evaluation of the tumor burden by H&E staining." (PMID 37779142, 2023). "The protein levels of Sirt1 in lung tumors from KrasLA2_G12D mice were much higher than those in the corresponding tumor-adjacent normal tissues and in normal control lung tissue from KrasLA2_WT mice." (PMID 37779142, 2023). "Among them, miR-30e-5p, a well-known tumor suppressor that suppresses tumorigenesis via the Sirt1/JAK/STAT3 signaling pathway, was downregulated in both AIS/MIA and invasive adenocarcinoma compared with benign PNs." (PMID 35366907, 2022). "Resveratrol is a natural polyphenol compound that is a SIRT-1 activator with anti-inflammatory, antiviral, antibacterial, antifungal inhibitory abilities as well as cardiovascular and anti-tumor protective effects." (PMID 35222035, 2022). "SIRT1 is known to regulate oncogenic signals and play a role in the formation of the appropriate microenvironment for tumor cell survival." (PMID 36142156, 2022). "According to the results of our meta-analysis, the pooled effect indicated that SIRT1 overexpressed in tumor infiltration (T3 + T4), TNM stage (III + IV), and positive cases lymph node metastasis of ESCC (P < 0.05)." (PMID 35350833, 2022). "SIRT1 can also inhibit GC by repressing cell proliferation and thereby tumor growth, or by inducing a G1-phase cell-cycle arrest and cell aging by FOXO1/3, E2F1 and CDK4." (PMID 36499440, 2022). "Subsequently, the increased intranuclear expression of FOXO3a further enhanced the expression of ac-FOXO3a, which was induced via miR-124-3p.1 by targeting SIRT1, ultimately enhancing tumor cell apoptosis." (PMID 35013144, 2022). "In contrast, mice bearing xenograft tumors generated from cells harboring SIRT1‐S27A exhibited the tumor volume and the weight similar to those of mock control mice." (PMID 34826187, 2022). "Mechanistically, KIAA1429 stabilized the SIRT1 mRNA in an m6A-dependent manner, which consequently promotes tumor progression." (PMID 35217651, 2022). "They identified a subpopulation of tumor cells that exhibit strain-like properties, mitochondria-specific metabolic features, and expression of SIRT1 as a survival benefit." (PMID 36263432, 2022). "SIRT1 is abundant in liver CSCs and mediates carcinogenesis, tumor invasion, and tumor progression via deacetylation." (PMID 35674129, 2022). "The SIRT1 expression was lower in the tumor stage (I + II) than that in stage (III + IV) of ESCC (OR = 0.45, 95% CI: 0.32–0.63), and the difference was statistically significant (Z = 4.72, P < 0.05)." (PMID 35350833, 2022). "For example, NAMPT can inhibit SIRT-1 from preventing tumor migration and metastasis, while SIRT-1 can promote the consumption of NAD and enhance the role of NAMPTi." (PMID 35906622, 2022). "In vitro experiments, down-regulated expression of SIRT1 in TNBC cells inhibited tumor invasion, with altered expression of EMT-related proteins." (PMID 35927590, 2022). "All these findings indicated that Elaiophylin suppressed xenograft UM tumor growth by inhibiting SIRT1-mediated mitophagy." (PMID 35387119, 2022).
tumor (continued). "In the current study, we demonstrated that an EBV‐encoded miRNA, EBV‐miR‐BART18‐3p, significantly promotes tumor growth and facilitates de novo lipogenesis in CRC by regulating the SIRT1/HIF1α/LDHA/FASN axis." (PMID 36307872, 2022). "SIRT1, the most extensively studied mammalian sirtuin, regulates neuronal differentiation, tumor progression, apoptosis, DNA and chromosomal structure stability, gene expression, and cell cycle progression." (PMID 35054489, 2022). "Our further in vivo studies showed that Elaiophylin dramatically inhibited tumor growth in the human UM xenograft mouse model, which was accompanied with a decreased SIRT1 expression." (PMID 35387119, 2022). "SIRT1 has been shown to be present in the promoters of some tumor suppressor genes, leading to hyperacetylation of H4K16, which in turn induces the expression of these genes." (PMID 36476345, 2022). "For this reason, SIRT1 targeting is emerging as a potential strategy to improve different metabolic and/or inflammatory pathologies, as well as to prevent tumor initiation and progression." (PMID 36612000, 2022). "SIRT1 has been reported to affect various biological functions, including DNA repair, energy metabolism, tumor suppression, and mitochondrial homeostasis." (PMID 36176640, 2022). "The cases with positive SIRT1 expression were 252 among 415 cases in tumor infiltration (T3 + T4) of ESCC, with a positive rate of 60.72%." (PMID 35350833, 2022). "The expression of SIRT1 is positively correlated with tumor growth, chemo-resistance, and metastasis." (PMID 35217651, 2022). "On the one hand, SIRT1 inhibits tumor formation by inhibiting tumor promoters such as NF-κB and c-Myc." (PMID 35548580, 2022). "But some publication bias was observed in the analysis of SIRT1 expression and tumor size and age in ESCC (P < 0.05)." (PMID 35350833, 2022). "SIRT1 also plays a significant role in activating Wnt signaling acting as tumour promoter in colorectal cancer." (PMID 36505828, 2022). "Melatonin in tumor cells, such as human osteosarcoma, has been shown to inhibit SIRT1, resulting in increased pro-oxidant and antitumor activity." (PMID 36009340, 2022). "A number of studies support the tumor-promoting effect of SIRT1 and positive correlation of miRNA-21 with SIRT1 expression." (PMID 35441676, 2022). "First, we sought to clarify the dual role of SIRT1 as both a tumor suppressor and a promoter of tumor growth; secondly, we investigated the role of FoxO proteins during tumor progression and metastasis." (PMID 36142156, 2022). "For example, SIRT-1 is beneficial to maintain the dryness of liver cancer stem cells, while it can help restore anti-tumor immunity in TIME in the liver metastasis model of rectal cancer." (PMID 35906622, 2022). "Overexpression of SIRT1 promotes survival of cancer cells via inhibition of the synthesis of proteins and factors responsible for DNA repair and tumor suppressor factors as well as the inhibition of cell apoptosis." (PMID 35267521, 2022). "SIRT3 has also been suggested as a mitochondrial tumor suppressor, but overall, the main role of SIRT1 and SIRT3 in tumor suppression is controversial." (PMID 35629426, 2022). "Notable differences in the protein expression levels of ATPase, IDH2, LDHA, and SIRT1, as well as mtDNA amount, were detected between the samples of non-tumor adjacent tissue and tumor tissue from metastatic CRC patients." (PMID 35205159, 2022). "SIRT1 protein levels in whole cell lysates from tumor xenografts were variable across treatment groups." (PMID 35641987, 2022). "Studies looking at the expression of SIRT1 in BC indicate its contradictory roles as a tumor suppressor or promoter." (PMID 35203617, 2022). "The in vivo study in the A549-xenograft mice model showed that the anti-tumor effect of elaiophylin was accompanied by the decreased expressions of SIRT1, Nrf2, Parkin, and PINK1." (PMID 36497294, 2022).